AHR (aryl hydrocarbon receptor)
Diseases named in the same sentence as AHR in open-access papers (continued):
Sharing a sentence is not in itself a finding about the gene and the disease.
experimental autoimmune encephalomyelitis (34 papers, 2010 to 2025). An autoimmune demyelinating disease of the central nervous system that is produced experimentally in animals by the injection of homogenized brain or spinal cord in Freund's adjuvant. "Dietary tryptophan is an essential source of an aryl hydrocarbon receptor (AHR) agonist that limits CNS inflammation by reducing both astrocyte and microglial pathogenic activities and experimental autoimmune encephalomyelitis (EAE) development." (PMID 31952509, 2020). "AhR-deficient mice, for instance, develop more severe symptoms and disease scores in the experimental autoimmune encephalomyelitis model when compared with wild-type mice." (PMID 30090104, 2018). "For example, AHR activation by its high-affinity ligand TCDD in vivo suppresses the development of experimental autoimmune encephalomyelitis (EAE), experimental autoimmune uveoretinitis, and spontaneous autoimmune diabetes." (PMID 39308860, 2024). "For instance, in experimental autoimmune encephalomyelitis, two potent AhR agonists, TCCD and FICZ, have opposing effects in which the former decreases Th17 differentiation while the latter increases Th17 cells." (PMID 30944419, 2019). "This link of gut microbiome to CNS microglia was originally suggested by the fact that genetic knockout of the aryl hydrocarbon receptor (AHR) affected the progression of experimental autoimmune encephalomyelitis (EAE) in the mouse model." (PMID 30464763, 2018). "The AHR has been shown to modulate T-cell differentiation and effector functions in vitro and in experimental autoimmune encephalomyelitis (EAE), a murine model of MS." (PMID 30143013, 2018). "AhR activation during the induction of experimental autoimmune encephalomyelitis accelerates the onset and increases the pathology of this condition in wild-type mice, but not in AhR-deficient mice." (PMID 24966027, 2014). "The aryl hydrocarbon receptor (AhR) has been attributed with anti-inflammatory effects in the development of pathological immune responses leading to experimental autoimmune encephalomyelitis (EAE) via the induction of regulatory T cells." (PMID 24244565, 2013). "Here, activation of the AhR by either TCDD or ITE suppresses experimental autoimmune encephalomyelitis (EAE) yet is enhanced by FICZ." (PMID 24086407, 2013). "Similarly, in experimental autoimmune encephalomyelitis models, supplementation with Trp or Trp-derived AhR agonists enhanced IFN suppression and limit central nervous system (CNS) inflammation in an AhR-dependent mechanisms." (PMID 40761882, 2025). "In vivo experiments showed that FICZ treatment during induction of experimental autoimmune encephalomyelitis causes accelerated onset and increased pathology in wild-type mice, but not AhR-deficient mice." (PMID 24905409, 2014). "The AhR plays a crucial role in the gut–brain axis, which is increasingly recognized as a significant factor in the development and pathology of various neurological disorders, including multiple sclerosis (MS) and its animal model, experimental autoimmune encephalomyelitis (EAE)." (PMID 39767818, 2024). "Early experiments demonstrated that typical ‘AHR-core’ genes (genes consistently upregulated by AHR activation, including multiple xenobiotic metabolism enzymes such as Cyp1a1 and Cyp2a1) were induced in experimental autoimmune encephalomyelitis (EAE) mice treated with LAQ." (PMID 30893768, 2019). "In an experimental autoimmune encephalomyelitis model, CX3CR1+ microglia-specific AhR deletion upregulated the activation of proinflammatory astrocytes and aggravated inflammation, indicating that microglial AhR suppresses astrocytic inflammation." (PMID 36797786, 2023). "In mice with experimental autoimmune encephalomyelitis (EAE), AhR activation modulates both Treg and TH17 cell differentiation in a ligand-specific fashion." (PMID 32235789, 2020).
experimental autoimmune encephalomyelitis (continued). "The agonistic ligation of AhR by TCDD induces functional Treg cells, suppressing experimental autoimmune encephalomyelitis." (PMID 24966027, 2014). "Many AHR-mediated immunoregulatory mechanisms have been discovered, and this knowledge may enhance our understanding of the molecular pathogenesis of autoimmune inflammatory syndromes such as collagen-induced arthritis, experimental autoimmune encephalomyelitis, and experimental colitis." (PMID 25400638, 2014). "On the other hand, AhR activation by FICZ interferes with Treg development, boosts Th17 cell differentiation, and increases the severity of experimental autoimmune encephalomyelitis in mice." (PMID 24966027, 2014). "Further, experimental autoimmune encephalomyelitis (EAE) induction in mice lacking AhR expression resulted in increased inflammatory demyelination and clinical disability." (PMID 38167866, 2024). "AhR signaling activation during induction of experimental autoimmune encephalomyelitis (EAE) causes accelerated onset and increased pathology in wild-type mice, but not AhR-deficient mice." (PMID 32957545, 2020). "Moreover, AhR activation by 6-formylindolo [3, 2-b] carbazole (FICZ) enhanced Th17 differentiation and aggravated experimental autoimmune encephalomyelitis in mice." (PMID 26938767, 2016). "In experimental autoimmune encephalomyelitis (EAE), a common mouse model of Ms, gut metabolites derived from dietary tryptophan (Trp) were shown to activate astrocytic aryl hydrocarbon receptor (AHR) signaling, which limits NF-κB signaling and suppresses CNS inflammation." (PMID 34531726, 2021).
liver cancer (34 papers, 2011 to 2025). An epithelial or non-epithelial malignant neoplasm that arises from the liver. "This analysis revealed that AHR exerts broad regulatory effects on both non-coding and coding genes, with a common gene expression signature associated with liver cancer." (PMID 40248203, 2025). "We, therefore, evaluated AHR protein levels in a cohort of documented aflatoxin-associated liver cancers (AF-HCC) from patients with detectable levels of Aflatoxin M1 in their urine samples." (PMID 34373448, 2021). "Together, those results implicated that Kyn promoted IL-6 expression through AhR to promote liver cancer progression." (PMID 34657635, 2021). "Together, our study showed that the TDO2/Kyn/AhR/IL-6 signaling pathway was a novel mechanism underlying the malignancy of liver cancer, and suggested that AhR signals might be a valuable therapeutic target for tumor therapy." (PMID 34657635, 2021). "In addition to these, the results from our survival analysis using two independent clinical datasets clearly demonstrated that high AHR expression levels were strongly associated with good clinical outcomes in patients with liver cancer." (PMID 28878246, 2017). "In liver cancer cells, AHR was found to be critical in base excision repair where methylated cytosine was replaced by nonmethylated cytosine in the CYP1A1 promoter, leading to increased CYP1A1 RNA expression." (PMID 40765830, 2025). "Immunofluorescence and RNA-seq confirmed that AHR activation in liver cancer cells leads to nuclear translocation and gene regulation." (PMID 40248203, 2025). "In our model, the EVs likely delivered regulatory molecules that interfered with AhR signaling or gene transcription, pointing to their potential role in modulating xenobiotic metabolism in liver cancer cells." (PMID 41155323, 2025). "We assessed AHR activation and nuclear translocation in the liver cancer cell lines after FICZ treatment using immunofluorescence assays." (PMID 40248203, 2025). "This positions AhR as a key regulator in both metabolic liver diseases and liver cancer, with therapeutic potential in targeting AhR signaling for the treatment of these conditions." (PMID 39767818, 2024). "In summary, these data illustrate that the tumor modulatory functions of AhR in liver cancers remain to be fully understood." (PMID 38807762, 2024). "Collectively, this study is aimed at investigating the specific effects and mechanism of ZNF165/AhR/CYP1A1 on liver cancer cell aggressiveness." (PMID 35692498, 2022). "IL-6 is transcriptionally induced via the AhR, which was involved in the progenitor/stem cells proliferation in liver cancer." (PMID 34657635, 2021). "Inhibition of AhR signals exhibited improved tumor suppressive effects, which described novel sight for liver cancer therapy." (PMID 34657635, 2021). "Our study further provided evidence to suggest the TDO2 was equally capable of producing Kyn to mediate the AhR pathway activation in liver cancer cells." (PMID 34657635, 2021). "TDO2 expression in tumor cells accounted for the release of kynurenine (Kyn), which activated aryl hydrocarbon receptor (AhR) to promote liver cancer cells proliferation." (PMID 34657635, 2021). "As TDO2 expression contributed to liver cancer progression through Kyn/AhR/IL-6 signaling, we next examined the effects of combination therapy using AhR inhibitor PDM2 together with chemotherapeutic DOX or 5-FU." (PMID 34657635, 2021). "AFB1 exhibited even stronger toxic effects in liver cancer cells overexpressing AHR liver cancer cells (OE AHR)." (PMID 34373448, 2021). "Based on the dynamic nature of AHR levels revealed in this work, especially in response to AFB1-related stimuli, we propose the use of AHR as a monitor for the risk in developing liver cancer." (PMID 34373448, 2021).
liver cancer (continued). "The level of AHR is reportedly significantly elevated in various forms of cancer, including breast, ovarian, and liver cancers, and the AHR target genes of CYP1A1 and CYP1A2 are also linked to prognosis." (PMID 34373448, 2021). "In mechanism, we found that activation of AhR contributed to the upregulation of IL-6, which further promotes liver cancer development through a STAT3 and NF-kB/TIM4 dependent manner." (PMID 34657635, 2021). "Using liver cancer cell lines and subcutaneous mice models, we demonstrated that Kyn produced by TDO2/Trp metabolism activated AhR/IL-6 pathway in liver cancer, eventually resulting in upregulation of the NF-kB/TIM4/STAT3 signals and cancer development." (PMID 34657635, 2021). "Inhibition of AhR suppressed the cell proliferation induced by Kyn, as well as the colony formation, indicating that Kyn mediated AhR activation to promote liver cancer development." (PMID 34657635, 2021). "In liver cancer cells, over-expression of CYP1A1 induced by plant natural products has been associated with Aryl-hydrocarbon Receptor transformation." (PMID 32730293, 2020). "Despite BAI being an AHR agonist and upregulating CYP1A1 expression in human HepG2 liver cancer cells, it paradoxically reduces the AHR-mediated CYP1A1 expression induced by 7,12-dimethylbenz[a]anthracene (DMBA)." (PMID 32526964, 2020). "Together, our results reveal a novel link between NR2E3, AHR, and liver cancer via LSD1-mediated H3K4me2 histone modification in liver cancer development." (PMID 28878246, 2017). "We further demonstrated that higher expression of NR2E3 or AHR in liver cancer patients is strongly correlated with good clinical outcomes." (PMID 28878246, 2017). "Lastly, we demonstrated that both AHR and NR2E3 are significantly associated with good clinical outcomes in liver cancer." (PMID 28878246, 2017). "The AhR-VEGF pathway through ATF4 is a novel pathway in glucose-deprived liver cancer cells that is related to the microenvironment within a cancer tissue affecting liver cancer malignancy." (PMID 24330582, 2013). "To study the role of AHR in liver cancer, we induced AHR activation in HCC cells using 200 nM FICZ." (PMID 40248203, 2025). "It has been shown that AhR is highly expressed in human liver cancer tissues and cell lines." (PMID 38807762, 2024). "The tumor modulatory role of AhR is well-appreciated in liver cancers but remains controversial." (PMID 38807762, 2024). "Inhibition of AhR signaling by PDM2 attenuated tumor growth in a xenograft model of liver cancer." (PMID 37876966, 2023). "Moreover, we discuss AHR as a potential therapeutic target in hepatic disorders, including autoimmune liver disease, liver fibrosis, and liver cancer." (PMID 34075438, 2021). "First, we analyzed AHR mRNA levels in the array data from 424 liver cancers in the TCGA database." (PMID 34373448, 2021). "AHR or HDAC8 overexpression in liver cancer cells speeds cell proliferation." (PMID 29301348, 2018). "Previous studies emphasized that abnormal AHR expression and activation inhibited the functional expression of anti-oncogenes and altered cell survival, proliferation, and differentiation in breast and liver cancer cells." (PMID 30144817, 2018). "Putative liver stem cells – known as “oval cells” in the rat and “progenitor cells” in the human, may be one possible link between early events in AhR toxicity pathway activation and eventual cell proliferation culminating in liver cancer." (PMID 23248599, 2012). "Interestingly, there are also mixed findings regarding endogenous AhR activity in liver cancers." (PMID 38807762, 2024). "However, PDM2 obviously strengthened the anticancer effects of DOX, indicating that suppression of AhR could efficiently improve the outcome of chemotherapy, describing a novel strategy for liver cancer treatment." (PMID 34657635, 2021). "Thus, we sought to validate the hypothesis that Kyn promoted liver cancer development through an AhR dependent manner." (PMID 34657635, 2021).
liver cancer (continued). "Thus, we examined whether AHR levels are significantly correlated with prognosis in human liver cancer development." (PMID 28878246, 2017). "However, the clinical association of AHR with human liver cancer has not yet been firmly established." (PMID 28878246, 2017). "In spite of the large number of empirical studies with TCDD, some of which are summarized above, there is no agreement on a unifying hypothesis to connect these observations into a mechanistic description linking AhR toxicity pathway activation to liver cancer." (PMID 23248599, 2012). "So far, TCDD is known to directly induce Serpine1 through an AhR- and ARNT-dependent mechanism in mouse liver cancer cell lines." (PMID 39596044, 2024). "The potential effects of AhR on the expression of IFN and ISGs were investigated using human lung epithelial cell line H1299 and human liver cancer cell line HepG2, which express ACE2 and can be infected by SARS-CoV-2." (PMID 37256962, 2023). "In this study, we identified a novel mechanism in which TDO2, through Trp/Kyn metabolism, activated AhR/IL-6/STAT3/NF-kB signaling and promoted liver cancer progression." (PMID 34657635, 2021). "To explore the contribution of AhR activation to tumor progression, we used PDM2, an AhR inhibitor, to treated liver cancer cells cultured with Kyn." (PMID 34657635, 2021). "When liver cancer cells or mouse liver cells are treated with TCDD, a ligand of AHR, nuclear translocation of AHR turns on downstream genes, including HDAC8." (PMID 29301348, 2018). "Here, we found that an orphan nuclear NR2E3 maintains AHR expression, and forms an active transcriptional complex with transcription factor Sp1 and coactivator GRIP1 in MCF-7 human breast and HepG2 liver cancer cell lines." (PMID 28878246, 2017). "Despite the poor correlation between AHR expression and liver cancer occurrence based on the TCGA data, our work revealed that AHR protein levels increase in response to AFB1-adduct formation, highlighting its importance in studying aflatoxin-related liver cancer." (PMID 34373448, 2021). "Collectively, these results showed for the first time that both AHR and NR2E3 are good prognostic indicators and may function as tumor suppressor genes during the development of liver cancer." (PMID 28878246, 2017). "The pathway from AhR to VEGF through ATF4 is a novel pathway in glucose-deprived liver cancer cells, which is related to the microenvironment within cancer tissue that affects liver cancer malignancy." (PMID 24330582, 2013). "The aryl hydrocarbon receptor (AhR) data was also included because of its potential role in xenobiotic metabolism and non-genotoxic liver cancer." (PMID 21339822, 2011). "Furthermore, the downregulation of ZNF165 could significantly decrease the expression of AhR, CYP1A1, and CYP1B1 in liver cancer cells." (PMID 35692498, 2022). "The connection between AHR and AFB1-HCC, addressed by this work, is particularly relevant to the current clinical practices in combating HCC, especially when considering that the incidence of liver cancer has remained alarmingly high in China with limited options for effective therapies." (PMID 34373448, 2021). "In conclusion, we revealed a nongenomic AhR mechanism that may account for the modulated progression of liver cancer after phthalate exposure." (PMID 25081364, 2014).